ATF4 (activating transcription factor 4)
Diseases named in the same sentence as ATF4 in open-access papers (continued):
Sharing a sentence is not in itself a finding about the gene and the disease.
osteonecrosis (1 paper, 2017). A none disease characterized by death of bone tissue due to a lack of blood supply. "The result in this study showed that osteonecrosis elevated the level of p-eIF2α and ATF4." (PMID 28698612, 2017).
pancreatitis (1 paper, 2021). Inflammation of the pancreas. "A box plot of the data from the microarray dataset GSE3644 found that ATF4 was highly expressed in pancreatitis." (PMID 33414424, 2021).
parasite infection (1 paper, 2023). "Cytoprotective autophagy genes, ATG5 and ATG7, are known to be upregulated as a result of PERK/ATF4 pathway activation, which favors cellular survival and parasite infection." (PMID 37152895, 2023).
pheochromocytoma (1 paper, 2020). "RNA expression levels of RET gene with other pheochromocytoma-related genes and UPR markers, Bip/GRP78, CHOP, ATF4, and ATF6, in her pheochromocytoma relative to her normal adrenal gland were analyzed by real time PCR (RT-PCR)." (PMID 32571297, 2020). "Those of unfolded protein response markers, Bip/GRP78, CHOP, ATF4, and ATF6, were also increased in the pheochromocytoma." (PMID 32571297, 2020).
pneumoconiosis (1 paper, 2025). An occupational lung disorder caused by inhalation of dust particles. "miR-205-5p in pulmonary extracellular vesicles mediates the development of nodular thyroid disease associated with coal worker’s pneumoconiosis through the ATF4/CHOP signaling axis." (PMID 40687582, 2025). "Further research is essential to comprehensively investigate the specific targets through which miR-205-5p derived from pulmonary extracellular vesicles triggers the development of nodular thyroid disease associated with coal worker’s pneumoconiosis via the ATF4/CHOP signaling axis." (PMID 40687582, 2025). "Furthermore, the expression levels of ATF4 and CHOP were also significantly increased in coal worker’s pneumoconiosis patients (P<0.01), consistent with the expression trend of miR-205-5p." (PMID 40687582, 2025). "This study focuses on whether pulmonary extracellular vesicles in coal worker’s pneumoconiosis (CWP) patients contain miR-205-5p and whether it influences the development of nodular thyroid disease (NTD) by regulating the ATF4/CHOP signaling axis." (PMID 40687582, 2025).
psoriasis (1 paper, 2023). An autoimmune condition characterized by red, well-delineated plaques with silvery scales that are usually on the extensor surfaces and scalp. "Furthermore, the inflammatory indicators found to be upregulated in psoriasis MCs, such as ATF4, CXCL12, LTA, TACR1, TLR4, and CTSB, interestingly share IL-1β as a common modulator." (PMID 37681909, 2023).
Reovirus Infection (1 paper, 2020). "This suggests a mode of action where GSK2606414 in the context of reovirus infection enhances eIF2a-ATF4 signaling supporting enhanced viral protein production." (PMID 32128359, 2020). "After reporter validation, ATF4, IRE1, and ATF6 reporter levels were imaged after 72 h of reovirus infection and GSK2606414 treatment." (PMID 32128359, 2020). "In the context of reovirus infection, GSK2606414 induced eIF2a-ATF4 signaling." (PMID 32128359, 2020). "Unlike in combination with thapsigargin, in the context of reovirus infection, GSK2606414 can increase signaling through eIF2a-ATF4." (PMID 32128359, 2020).
retinal ischemia (1 paper, 2015). A ischemic disease that involves the retina. "At 3 and 24 h after retinal ischemia, expression of ER stress markers (GRP78, CHOP, and ATF4) was significantly increased, indicating that ER stress was elevated in our model." (PMID 26448323, 2015).
rheumatoid arthritis (1 paper, 2021). A chronic, systemic autoimmune disorder characterized by inflammation in the synovial membranes and articular surfaces. "As a result, expression of ATF4, PSPH, and ASCT1 was upregulated in peripheral blood mononuclear cells of patients infected with rotavirus 21 and in synovial macrophages in patients with rheumatoid arthritis 22 compared to their respective healthy controls." (PMID 34045514, 2021).
Right ventricular hypertrophy (1 paper, 2023). In this case the right ventricle is more muscular than normal, causing a characteristic boot-shaped (coeur-en-sabot) appearance as seen on anterior- posterior chest x-rays. "Furthermore, GLY, 4-PBA and VK3 administration attenuated the increases of RVSP, mPAP and RV/(LV+S), right ventricular hypertrophy, and pulmonary vascular remodeling by targeting on PERK/ATF4/SIAH2/HIPK2 pathway in PAH rats." (PMID 37268944, 2023).
SARS-CoV infection (1 paper, 2022). "EIF2 phosphorylation, ATF4, and CHOP upregulation are observed after SARS-CoV infection, resulting in PERK activation." (PMID 36523813, 2022).
skin aging (1 paper, 2023). The gradual irreversible changes in structure of skin that occur as a result of the passage of time.. "Based on bioinformatics and machine learning techniques, we obtained three key CRGs, SIRT1, ARNTL and ATF4, which are potential risk genes for skin aging and are also associated with the alteration of immune microenvironment in skin aging." (PMID 37905958, 2023). "In conclusion, three key CRGs, including SIRT1, ARNTL, and ATF4, which are closely related to skin aging, were obtained based on bioinformatics and machine learning technology screening." (PMID 37905958, 2023). "We further investigated the expression profiles of SIRT1, ARNTL and ATF4 in skin aging." (PMID 37905958, 2023). "Based on machine learning, we identified three key CRGs closely related to skin aging, namely SIRT1, ARNTL and ATF4." (PMID 37905958, 2023). "Three key skin aging-related CRGs, SIRT1, ARNTL, and ATF4, were identified based on machine learning." (PMID 37905958, 2023).
spinal cord injury (1 paper, 2023). Penetrating and non-penetrating injuries to the spinal cord resulting from traumatic external forces (e.g., WOUNDS, GUNSHOT; WHIPLASH INJURIES; etc.). "The integrated stress response (ISR)-activated transcription factors ATF4 and CHOP/DDIT3 may regulate oligodendrocyte (OL) survival, tissue damage and functional impairment/recovery in white matter pathologies, including traumatic spinal cord injury (SCI)." (PMID 37280306, 2023).
squamous cell carcinoma (1 paper, 2018). A carcinoma arising from squamous epithelial cells. "The protein level of PDL1 was significantly correlated with those of IRF1, eIF2α, and ATF4 in the tissues of all subjects and the subgroup of squamous cell carcinoma but not in the normal tissue of adenocarcinoma." (PMID 30305853, 2018).
synucleinopathies (1 paper, 2024). "Collectively, ATF4 might play a crucial role in JNK-facilitated neuronal apoptosis in cortical neurons with synucleinopathies." (PMID 38444039, 2024).
systemic lupus erythematosus (1 paper, 2021). An autoimmune multi-organ disease typically associated with vasculopathy and autoantibody production.
temporal lobe epilepsy (1 paper, 2017). A localization-related (focal) form of epilepsy characterized by recurrent seizures that arise from foci within the temporal lobe, most commonly from its mesial aspect. "Recently, the PI3K/Akt/GSK3β/eIF2α/ATF4 pathway was shown to be responsible for increased xCT expression in the hippocampus of patients suffering from temporal lobe epilepsy." (PMID 28086920, 2017).
thalassemia (1 paper, 2024). An inherited blood disorder characterized by a decreased synthesis of one of the polypeptide chains that form hemoglobin. "Our study reveals the loss-of-function of miR-214 during translational activation of activating transcription factor 4 mRNA, leading to decreased reactive oxygen species levels and increased glutathione levels in thalassemia erythroid cell." (PMID 38625890, 2024). "In our study, downregulation of ATF4 mRNA level was observed in both the thalassemia groups—this implied that miR-214 might lead to downregulation of ATF4, which could further promote oxidative stress." (PMID 38625890, 2024). "Our study revealed that the loss of function of miR-214 leads to a reduction in translational activation of ATF4 mRNA and a subsequent decrease in ROS levels and increase in GSH levels in thalassemia erythroid cells." (PMID 38625890, 2024).
thyroid papillary carcinoma (1 paper, 2025). "This study analyzed the effects of exosomes (EXo) and their cargo, microRNA-205-5p (miR-205-5p), on the expression of key apoptosis-related proteins—BAX, caspase-3, ATF4, and CHOP—in thyroid papillary carcinoma cells." (PMID 40687582, 2025).
thyroid tumours (1 paper, 2020). "These mutations synergistically drive the occurrence of thyroid tumours through the ATF4 and c‐MYC pathways." (PMID 32926483, 2020).
type-3 Gaucher disease (1 paper, 2024). "Our finding further indicates an elevation in the expression of UPR genes and proteins like BiP, CHOP, and ATF4, suggesting an increase in ER stress in the iPSCs-derived neuronal cells of individuals with type-3 Gaucher disease (GD)." (PMID 38649404, 2024).
Urinary incontinence (1 paper, 2021). Loss of the ability to control the urinary bladder leading to involuntary urination. "In addition, Li-ESWT could also activate urethral muscle-derived stem cells, enhance myogenesis, and improve urinary incontinence by activating the PERK/ATF4 pathway." (PMID 33628099, 2021).
uveal melanoma (1 paper, 2020). A melanoma derived from melanocytes of the uveal tract. "Our results indicate that the protective effect mounted by Mel270 and 92.1 uveal melanoma cells in response to ABT-263 specifically involved the PERK/EIF2α/ATF4 signaling cascade." (PMID 32337074, 2020).
uveitis (1 paper, 2024). An inflammatory process affecting a part of or the entire uvea. "Moreover, FTO shows uveitis curing effects by modulating m6A level of ATF4 to suppress inflammatory cytokine secretion and maintain tight junctions in RPE cells." (PMID 38297099, 2024).
vascular ED (1 paper, 2024). "The endoplasmic reticulum (ER) stress, linked with vascular ED, includes the activation of the inositol requiring enzyme 1 (IRE1) and activating transcription factor 6 (ATF6) pathways, and the induction of activating transcription factor 4 (ATF4)." (PMID 38172976, 2024).
tumor (436 papers, 2005 to 2026). "These tumor-supportive effects of ATF4 have been shown to be mediated by cancer-associated fibroblasts." (PMID 40616124, 2025). "This ATF4-mediated upregulation of LDHA leads to lactate accumulation in the tumor microenvironment, causing acidification that suppresses immune cell activity and facilitates immune evasion." (PMID 40830338, 2025). "The oncogenic properties of BZW2 are associated with the translation of ATF4, another transcription factor, delaying the restart and thus promoting the survival of stress-exposed tumor cells." (PMID 40070829, 2025). "On the one hand, tumor cells often use ATF4 to reduce stress caused by rapid proliferation and nutrient restriction in the growing tumor mass." (PMID 39819316, 2025). "By restricting CAR expression in T cells to the tumor microenvironment in an ATF4-dependent manner, the 2xAARE-YB system reduces the risk of on-target, off-tumor toxicity." (PMID 40335738, 2025). "In fact, ATF4 is often utilised in tumour cells to reduce stress caused by rapid proliferation and nutrient deficiency." (PMID 38652216, 2024). "Based on the immune infiltration feature in the TIMER2 database, the ATF4 signaling score had an association with the activated immune tumor microenvironment in tumors." (PMID 39139391, 2024). "The high level of ROS caused by tumor microenvironments such as hypoxia increases the uptake of exogenous cystine/cysteine by activating ATF4 axis." (PMID 39079386, 2024). "Previous studies have shown that lower BCAA levels elicit compensatory upregulation of LAT1 by the transcription factor ATF4 in tumor cells, suggesting a potential causal relationship between BCAA deficiency and LAT1 increase." (PMID 38946582, 2024). "In MM the PERK-eIF2α-ATF4-CHOP ER stress response has been linked by many groups to elevated tumor cell killing." (PMID 38441437, 2024). "We also examined the relationships between the ATF4 signaling score level and microsatellite instability and tumor mutation burden, which were proposed to be related to the prognosis for various tumors after receiving immunotherapy." (PMID 39139391, 2024). "They show that released cytochrome c promotes translation of the ISR transcription factor ATF4 and causes drug-treated tumor cells to survive." (PMID 36669100, 2023). "Treatment with PERK inhibitor, AMG-44 at high concentrations resulted in activation of the alternative ISR kinase, GCN2 and induced levels of p-eIF2 and ATF4 in both tumor cells and cancer-associated fibroblasts (CAFs)." (PMID 37181357, 2023). "p38, STAT3, ERK1/2, and JNK phosphorylation were generally higher in ATF4-deficient tumours, which expressed more EREG but less FGF21 mRNA." (PMID 36996941, 2023). "Overexpression of ATF4 has been linked to cancer cell proliferation, invasion, stemness, poor prognosis, higher tumor grade, therapy resistance, and shorter survival in a variety of cancers." (PMID 37817771, 2023). "Similar results were obtained in B16F10 tumours (about 1,000 mm3), which showed a persistent vascularization defect after ATF4 loss." (PMID 35654839, 2022). "Tumours grown in ATF4 knockout (KO) mice exhibit deficiencies in markers of CAF activation, a significant reduction in the expression and biosynthesis of type I collagen and secretion of critical pro-angiogenic cytokines." (PMID 35654839, 2022). "Col1a1-driven-specific ATF4 deletion caused a significant growth delay in B16F10 tumours, similar to that observed in Atf4Δ/Δ mice." (PMID 35654839, 2022). "Collectively, our data revealed that ATF4 expression was strongly associated with tumor aggressiveness and overall survival in GC patients." (PMID 34976799, 2021). "Here we identified ER stress as another tumor-associated stress signal that stimulates PHLPP degradation to potentiate eIF2α/ATF4 signaling." (PMID 34663797, 2021). "Recent advancements point to a role for ATF4 mutations in mediating drug resistance in tumor cells featured by xCT overexpression." (PMID 31534554, 2019).
tumor (continued). "In this study, we found that downregulation of E-cadherin is pivotal in ATF4-induced cell migration, in keeping with numerous reports that loss of E-cadherin expression is critical for cell migration and tumor metastasis." (PMID 31064130, 2019). "Then, western blot analysis was used to assess the expression of P-Stat3, Stat3, and ER stress-associated protein ATF4 in MDSCs obtained from the spleens of tumor-bearing mice." (PMID 27655678, 2016). "We conclude from these experiments that, across different cell lineages, tumor suppressor BTG1 acts as an enhancer of ATF4 mediated stress responses, while a loss of BTG1 function promotes cellular survival in response to nutrient stress." (PMID 26657730, 2016). "Nupr1 has also been implicated in mediating cannabinoid-induced apoptosis of tumor cells through upregulation of the ERS-related genes ATF4, Chop and Trib3 (tribbles pseudokinase 3)." (PMID 27031958, 2016). "The activating ATF4-mutation here leads to an increase in xCT-expression in tumor cells and reduction in ATF4 levels is conversely associated with a diminished xCT-expression." (PMID 25228443, 2014). "Importantly, restoring ATF4 levels leads to glycolytic metabolic reprogramming in tumor cells and counteracts the anti-tumor effects caused by METTL1 knockdown." (PMID 40809384, 2025). "Reduced ATF4 translation in METTL5‐deficient OC cells enhances tumor ferroptosis." (PMID 41042068, 2025). "Tumor microenvironment could activate eIF2α-ATF4 axis through several ways such as hypoxia-induced ROS causing ER stress to activate PERK, or amino acid limitation to activate GCN2." (PMID 39079386, 2024). "Collectively, exploring the underlying mechanisms of ATF4-induced transcriptional program and its effects on cellular adaptation may provoke novel therapeutic target for anti-tumor strategy." (PMID 38601083, 2024). "Additionally, knockdown of ATF4 in human cancer cell-mouse xenografts caused a large reduction in tumour mass compared to control cell xenografts." (PMID 36825279, 2023). "In addition, the suppression of ATF4 expression in the context of amino acid deprivation and glucose deficiency inhibits tumour survival and proliferation in the HeLa human cervical cancer cell line." (PMID 36852470, 2023). "ATF4 was identified for regulating major amino acids of collagen, thus driving cancer-associated fibroblasts’ function for shaping the extracellular matrix to support tumor progression and metastasis." (PMID 37601686, 2023). "Tumour regression in vivo and in vitro was associated with the induction of ATF4 and inhibition of the mTORC1 pathway in mouse tumour explants By means of in vitro silencing experiments, we have shown that ATF4 inhibited the mTORC1 signalling pathway through Sestrin2 − a well-known ATF4 target gene." (PMID 35367410, 2022). "Taken together, these results suggest that ATF4 loss in fibroblasts impairs their pro-angiogenic activity through a defective secretome, which leads to abnormal angiogenesis and significant attenuation of tumour growth." (PMID 35654839, 2022). "We hypothesized that the severe phenotype of reduced collagen levels in tumours grown in ATF4-deficient mice could also involve additional steps in the pathway." (PMID 35654839, 2022). "Furthermore, the chi-square test confirmed that the level of ATF4 was strongly associated with tumor stage, tumor size, tumor depth, and lymph node metastasis (p < 0.05)." (PMID 34976799, 2021). "Additionally, we investigated the association of INPPL1, BTBD3 and ATF4 expression with histological tumor parameters such as Breslow thickness and ulceration as well as with patient gender and age at diagnosis." (PMID 32179834, 2020). "Up-regulation of ATF4 due to p62 deficiency in the tumor stroma enhances glucose carbon flux through a pyruvate carboxylase-asparagine synthase cascade, which in turn results in asparagine generation as a compensatory source of the nitrogen required for proliferation of both cancer cells and CAFs." (PMID 31067787, 2019).